BIRC7 (baculoviral IAP repeat containing 7)
Description:
Apoptotic regulator capable of exerting proapoptotic and anti-apoptotic activities and plays crucial roles in apoptosis, cell proliferation, and cell cycle control. Its anti-apoptotic activity is mediated through the inhibition of CASP3, CASP7 and CASP9, as well as by its E3 ubiquitin-protein ligase activity. As it is a weak caspase inhibitor, its anti-apoptotic activity is thought to be due to its ability to ubiquitinate DIABLO/SMAC targeting it for degradation thereby promoting cell survival. May contribute to caspase inhibition, by blocking the ability of DIABLO/SMAC to disrupt XIAP/BIRC4-caspase interactions. Protects against apoptosis induced by TNF or by chemical agents such as adriamycin, etoposide or staurosporine. Suppression of apoptosis is mediated by activation of MAPK8/JNK1, and possibly also of MAPK9/JNK2. This activation depends on TAB1 and MAP3K7/TAK1. In vitro, inhibits CASP3 and proteolytic activation of pro-CASP9. [Isoform 1]: Blocks staurosporine-induced apoptosis. Promotes natural killer (NK) cell-mediated killing. [Isoform 2]: Blocks etoposide-induced apoptosis. Protects against natural killer (NK) cell-mediated killing.
Synonyms: KIAP; ML-IAP; LIVIN; MLIAP; RNF50
Tractability: Small molecule: a structure with a bound ligand is known; a high-quality ligand is known; it has a high-quality binding pocket. PROTAC: UniProt records ubiquitination sites on it; a small molecule that binds it is known.
Target class: Enzyme
Gene: Protein-coding gene on chromosome 20 (63,235,883 to 63,240,495, forward strand). Ensembl gene ENSG00000101197.
Subcellular location: Nucleus; Cytoplasm; Golgi apparatus
Subcellular location (Human Protein Atlas): Nucleoplasm; Centrosome; Cytosol
Pathways (Reactome):
Developmental Biology: Regulation of MITF-M-dependent genes involved in apoptosis
Gene Ontology:
Molecular function: protein binding; ubiquitin protein ligase activity; ubiquitin-protein transferase activity; cysteine-type endopeptidase inhibitor activity; cysteine-type endopeptidase inhibitor activity involved in apoptotic process; enzyme binding
Biological process: negative regulation of apoptotic process; negative regulation of tumor necrosis factor-mediated signaling pathway; positive regulation of JNK cascade; protein ubiquitination; regulation of apoptotic process; regulation of cell population proliferation; regulation of natural killer cell apoptotic process; positive regulation of protein ubiquitination; regulation of cell cycle
Cellular component: centrosome; cytoplasm; cytosol; Golgi apparatus; nucleoplasm; nucleus
Genetic constraint (gnomAD): Loss-of-function variants: 26 observed, 30.58 expected, observed/expected ratio (o/e) 0.85, 90% interval 0.62 to 1.18. The upper end of that interval is the gene's LOEUF score, 1.18, which puts it in group 5 of 6, group 1 being the genes least tolerant of losing a copy. Missense variants: 409 observed, 375.31 expected, observed/expected ratio (o/e) 1.09, 90% interval 1 to 1.18. Synonymous variants: 176 observed, 158.86 expected, observed/expected ratio (o/e) 1.11, 90% interval 0.98 to 1.25.
Homologues: Orthologues: chimpanzee BIRC7 (98% identical), rabbit BIRC7 (69% identical), guinea pig BIRC7 (66% identical), dog BIRC7 (65% identical), macaque BIRC7 (64% identical), mouse Birc7 (64% identical), rat Birc7 (61% identical), zebrafish birc7 (38% identical), Drosophila melanogaster Diap2 (32% identical), Caenorhabditis elegans bir-2 (17% identical). Paralogues in human: BIRC2 (39% identical), BIRC3 (38% identical), BIRC6 (31% identical), NAIP (30% identical), XIAP (29% identical), NLRC4 (18% identical), BIRC5 (12% identical).